CGAS (cyclic GMP-AMP synthase)
Diseases named in the same sentence as CGAS in open-access papers (continued):
Sharing a sentence is not in itself a finding about the gene and the disease.
cancer (continued). "Consequently, a deficiency in cGAS could hypothetically result in unchecked cellular growth and cancer formation." (PMID 39050748, 2024). "However, long‐term inhibition of cGAS–STING signal activity may increase the risk of pathogenic microbial infection or cancer." (PMID 38525112, 2024). "In addition, we systematically analyzed the cancer-associated cGAS mutations through data mining." (PMID 38086852, 2023). "The Cancer Genome Atlas (TCGA) database was screened to identify BC-related mutations (apart from oncogenes), targeting, in particular, TLRs, the adaptor molecule MyD88, and the cGAS-STING (cyclic GMP-AMP synthase-stimulator of interferon genes) immune pathway." (PMID 40778061, 2023). "Furthermore, some cancer-associated cGAS mutations abolished the effect of cGAS on L1 repression through disrupting different steps of the CHK2-cGAS-TRIM41-ORF2p regulatory axis, suggesting that cGAS may act as a tumor suppressor." (PMID 38086852, 2023). "Indeed, cGAS deletion accelerated spontaneous immortalization of cells, which might be linked to several human diseases, including cancer and age-related diseases." (PMID 37345163, 2023). "Interestingly, conventional cancer treatments including radiation and certain chemotherapy, which cause various forms of DNA damage and genomic instability, also activate the cGAS pathway and generate antitumor-immune responses." (PMID 36442099, 2022). "Thus cGAS-deficient cells are highly sensitive to radiation and cancer therapeutics." (PMID 33643304, 2020). "Thus, it is logical to choose oncolytic virus strategy for cGAS-STING-deficient cancer patients." (PMID 30935414, 2019). "Based on its function, cGAS–STING can both directly prevent cancer cell proliferation and promote immune cell-mediated cell death." (PMID 40770563, 2026). "As cancer cells evolve, cGAS–STING activity can induce either the type I IFN response or canonical NF-κB-dependent cytokine signaling." (PMID 40770563, 2026). "Therefore, epigenetic silencing may underlie the loss of cGAS expression in cancer cells." (PMID 41509453, 2026). "To understand why cGAS or STING expression was lost in these cancer cells, we measured the methylation status of their genomic loci by bisulfite DNA sequencing." (PMID 41509453, 2026). "Our studies confirm the impairment of the cGAS-STING signaling pathway in various cancers and identifies DNA methylation-induced silencing of the cGAS or STING genes as a potential cause of this damage." (PMID 40830678, 2026). "In the context of cancer, upon engagement by DNA, the cGAS-STING pathway can impact virtually all aspects of tumorigenesis, from cancer cell transformation to metastasis." (PMID 40770563, 2026). "Together, our findings identify innate immune sensing as a natural barrier to ecDNA-driven oncogenesis and establish cGAS-STING reactivation as a therapeutic strategy for ecDNA+ cancers." (PMID 41509453, 2026). "Western blot (WB), Polymerase Chain Reaction (PCR), and immunofluorescence (IF) were employed to evaluate the effects of lactate on the expression of ESM1, Akt1, and Cyclic GMP-AMP Synthase (cGAS) pathway-related proteins in cancer cells." (PMID 41930148, 2026). "In a significant stride towards multimodal cancer therapy, integrating chemotherapy, sonodynamics and induction of immune response by activation of cGAS‐STING pathway represents a promising clinical and therapeutic approach." (PMID 41492185, 2026). "The release of self-DNA is able to access the cytosol of DCs to induce the secretion of cytokines by the activation of the cyclic GMP-AMP synthase (cGAS)/stimulator of interferon gene (STING) pathway (cancer development ensuing)." (PMID 39857785, 2025). "The accumulated dsDNA fragments escaped from cancer cells, thereby activating the cGAS‐STING signaling pathway and triggering a robust immune response." (PMID 40568953, 2025).
cancer (continued). "SMARCAL1 functions to limit endogenous DNA damage in cancer cells, thereby suppressing the activation of cGAS–STING-dependent signaling during cancer cell growth." (PMID 40629041, 2025). "Within cancers, cGAS–STING signaling links chromosomal instability to antitumor immunity but can also be co-opted by tumors, underscoring its context-dependent roles." (PMID 41373427, 2025). "Targeting the cGAS-STING pathway in cancer therapy is promising due to its critical role in activating immune responses, particularly through type I interferon production, which stimulates T-cell priming and immune cell infiltration into tumors." (PMID 39949780, 2025). "Further researches are essential to unravel the dual roles of cGAS-STING to maximize its clinical utility in cancer immunotherapy." (PMID 40052963, 2025). "Secondly, how ALDH1A3 affects other key cancer-related pathways through the cGAS–STING pathway remains to be further explored." (PMID 40227735, 2025). "In fact, many therapeutic targets of cancer and other diseases are selective autophagy substrates, such as cGAS and PD‐L1, among others." (PMID 39656940, 2025). "Other cGAS‐STING pathway molecules have been considered to be therapeutic targets for cancer treatment." (PMID 41117130, 2025). "Further, 5-FU can mediate aspects of its anti-cancer effects through the immune-activating cGAS/STING1 pathway." (PMID 40105196, 2025). "Given the critical roles of TRIM29 and TRIM18 in controlling cGAS-STING pathway and cancer development, it is deserved to investigate the role of TRIM29 and TRIM18 in controlling cGAS-STING pathway in cancers." (PMID 40552295, 2025). "In the context of cancer progression and chemotherapy response, both protective and detrimental effects of autophagy and the cGAS-STING pathway have been observed." (PMID 40445433, 2025). "By focusing on the development of novel STING agonists, strategic combination therapies, and actionable biomarkers, future research can provide clearer and more targeted solutions for overcoming current limitations in cGAS-STING-targeted cancer immunotherapy." (PMID 40052963, 2025). "The cGAS-STING signaling pathway has increasingly been recognized for its involvement in cancer development." (PMID 40507791, 2025). "Mechanistically, we demonstrated that OMVs act as natural STING agonists, specifically delivering internal dsDNA into cancer cells and triggering activation of the cGAS/STING/IRF3/IFN‐I axis and ICD occurrence." (PMID 40240911, 2025). "We previously showed that topotecan, a chemotherapeutic drug and topoisomerase I (TOP1) inhibitor, binds to ribosomal protein RPL15 and induces the secretion of DAMPs from cancer cells, which activate cGAS-STING signaling in dendritic cells." (PMID 41276688, 2025). "Targeting cGAS-STING-dependent immune signaling pathway has been proved to be an effective strategy to enhance anti-cancer immunity and sensitive tumors to ICBs therapy." (PMID 39990655, 2025). "Several compounds have already demonstrated therapeutic potential by targeting cGAS-STING in cancers." (PMID 40552295, 2025). "Emerging evidence has shown that ferroptosis is an upstream activator of the cGAS-STING pathway in multiple cancers." (PMID 40846966, 2025). "Insights into the biology of the cGAS-STING pathway have enabled the discovery of small-molecule agents which have the potential to activate cGAS-STING axis in cancers." (PMID 40552295, 2025). "Studies have demonstrated that cancer cells with downregulated cGAS-STING activity are able to evade immune surveillance." (PMID 41417876, 2025). "Pharmacological activation of the cGAS-STING pathway by cGAS-STING agonists to overcome cancer drug resistance offers substantial potential to promote antitumor immunity." (PMID 40846966, 2025). "Emerging evidence highlights the critical role of cGAS-IFN-I-mediated DNA sensing in cancer cells for initiating robust immune responses." (PMID 40282455, 2025).
cancer (continued). "In the context of cancer immunotherapy, cGAS–STING–mediated signaling promotes IFN-I production and chemokine release, thereby fostering an immunologically active TME." (PMID 41204180, 2025). "SN38-PROTAC treatment induced DAMP secretion from cancer cells, which activated cGAS-STING signaling in dendritic cells." (PMID 41276688, 2025). "To improve the efficacy of cancer immunotherapy, we employed the cGAS–STING agonist SR-717 in combination with the BiKE LILRB4/CD16A for treatment." (PMID 41417876, 2025). "Among immune-stimulating therapies, targeting the cyclic GMP-AMP synthase (cGAS)—stimulator of interferon genes (STING) pathway has emerged as an encouraging anti-cancer approach." (PMID 39857957, 2025). "The cGAS–STING pathway exhibits a paradoxical role in oncology, serving as both a critical regulatory factor for anti‐cancer immunity and a crucial mechanism underlying therapy resistance." (PMID 41275427, 2025). "Emerging research has revealed multiple E3 ubiquitin ligases as critical regulators of the cGAS-STING pathway in cancer biology." (PMID 40552295, 2025). "For instance, targeting PRMT9-mediated arginine methylation inhibits the maintenance of cancer stem cells and enhances antitumor immunity by activating cGAS-mediated IFN-I responses." (PMID 40166469, 2025). "Although not much is currently known regarding the specific functions of most of these lncRNAs, MAP3K20-AS1, STARD4-AS1 and PCAT1 are high-risk factors for different cancers and PCAT1 also is known to activate SOX2 as well as affect cGAS/STING signaling." (PMID 40018706, 2025). "Here, we demonstrated a combination treatment of DSF and Cu (DSF/Cu) robustly activated cancer cell-intrinsic cGAS-STING-dependent innate immune signaling pathway." (PMID 39990655, 2025). "In the context of altered sensing systems, cGAS/STING signaling was shown to be defective in numerous cancer cells." (PMID 40098954, 2025). "Concordantly, a recent study also confirmed that chromosomal instability induced cGAS–STING‐CCL2 pathway promotes downstream signal re‐wiring in cancer cells, which leading to a pro‐metastatic niche formation in lung." (PMID 39737867, 2025). "The integration of cGAS–STING agonists with immune checkpoint inhibitors holds substantial promise for reshaping the landscape of cancer immunotherapy." (PMID 41204180, 2025). "There have always been considerable challenges in using the cGAS-STING pathway as a target for cancer treatment." (PMID 40943568, 2025). "These insights highlight the complexity of cGAS-STING signaling across different cancer types and reinforce the need for patient stratification strategies, including genomic and epigenetic profiling, to optimize cGAS-STING-targeted therapies." (PMID 40052963, 2025). "New evidence reveals that the cGAS-STING axis is crucial in cancer development, impacting all aspects of tumorigenesis from initial malignancy to metastasis." (PMID 40552295, 2025). "The key molecules in the cGAS-STING signaling pathway can serve as predictive biomarkers to guide cancer treatment." (PMID 40052963, 2025). "PRMT1 has been found to methylate cGAS and prevent it from dimerizing, which attenuates the cGAS/STING signaling cascade in cancer cells." (PMID 40001488, 2025). "In cancer cells, genomic instability leads to the accumulation of cytosolic nucleic acids, activating the cyclic GMP-AMP synthase–stimulator of interferon genes (cGAS–STING) pathway and the expression and secretion of IFN-I." (PMID 40741921, 2025). "This reciprocal regulation of the cGAS–STING pathway challenges the traditional cancer suppressor‐centric perspectives." (PMID 41275427, 2025). "Studies have indicated that activation of the cGAS-STING pathway can induce senescence in cancer cells." (PMID 40621423, 2025). "IR700 loading boosted ICD induction in cancer cells upon irradiation and transactivated the cGAS/STING/IRF3/IFN‐I axis in TAMs by promoting the release of endogenous dsDNA from dying cancer cells." (PMID 40240911, 2025).
cancer (continued). "In this study, we identified a role of combined treatment of DSF and Cu (II) potently activating cGAS-STING-dependent innate immune signaling pathway in cancer cells by generating excessive ROS to induce DNA damage and cytosolic dsDNA releases." (PMID 39990655, 2025). "This section establishes that activation of the cGAS-STING pathway drives ferroptosis in multiple cancers through interconnected mechanisms: inducing autophagy (degrading GPX4), promoting mitochondrial fusion/mitophagy, and triggering ferritinophagy." (PMID 40846966, 2025). "The cGAS-STING axis serves as a crucial regulator of cancer immunity, with its mediated immune-supportive microenvironment potentially inhibiting malignant progression." (PMID 40846839, 2025). "Our study confirmed that engineered OMVs contained DNA from parental bacteria and efficiently stimulated the cGAS‐STING pathway in cancer cells and macrophages both in vitro and in vivo." (PMID 40240911, 2025). "Critical knowledge gaps remain as to why cGAS-STING signaling produces different outcomes on cancer progression." (PMID 40362284, 2025). "Ferroptosis has been identified as an upstream event that activates the cGAS/STING pathway in cancer." (PMID 40846966, 2025). "Several studies have demonstrated the importance of the cGAS-STING pathway in immunotherapy of human malignant tumors." (PMID 39975558, 2025). "Taken together, our data demonstrate that combined treatment of DSF and Cu robustly triggers cGAS-STING-mediated innate immunity in cancer cells." (PMID 39990655, 2025). "The transformation of NMs-based cGAS-STING therapies into reliable treatments has the potential to significantly enhance outcomes for cancer patients globally." (PMID 40831989, 2025). "He recently demonstrated a prototype of cancer metalloimmunotherapy by using manganese (Mn2+) that has been proven to effectively activate the cGAS-STING signaling pathway." (PMID 40008133, 2025). "Given the essential role of cGAS-STING signaling in the pathogenesis of cancers, drug discovery targeting the cGAS-STING axis has expanded rapidly." (PMID 40552295, 2025). "Emerging evidence have shown that activating of cGAS-STING pathway functions as a therapy to kill cancers." (PMID 40552295, 2025). "Collectively, these diverse approaches provide a comprehensive framework for effectively activating the cGAS-STING pathway in cancer immunotherapy." (PMID 40052963, 2025). "In summary, the cGAS-STING pathway holds significant potential for application in cancer therapy; however, its complexity necessitates a more nuanced and personalized approach in both research and clinical practice." (PMID 41438738, 2025). "Our findings demonstrate that ALDH1A3 gene knockout accelerated the cellular senescent-like phenotype, but inhibits SASP’s promoting effect on cancer by suppressing the cGAS–STING immune pathway." (PMID 40227735, 2025). "Tumors have the ability to escape immune surveillance by impairing cGAS transduction in cancer cells to accelerate tumorigenesis." (PMID 40001488, 2025). "The potential of G4 ligands in cancer immunotherapy lies in their ability to induce DNA damage, a process that is integral to triggering the cGAS-STING pathway and enhancing immunogenicity." (PMID 40333779, 2025). "From such we discuss recent research that highlights general mechanisms by which cGAS-STING contributes to cancers." (PMID 40552295, 2025). "In this context, the cGAS-STING pathway is under active investigation for its role in cancer-related immune responses." (PMID 40786100, 2025). "Expressions of cGAS-STING-related mRNAs in gastrointestinal cancers were analyzed using Gene Expression Profiling Interactive Analysis (GEPIA) based on The Cancer Genome Atlas (TCGA) database." (PMID 40786100, 2025). "The cyclic guanosine monophosphate‐adenosine monophosphate synthase (cGAS)‐stimulator of interferon genes (STING) pathway has emerged as a promising target for cancer immunotherapy." (PMID 40842018, 2025).
cancer (continued). "Cuproptosis is a newly discovered copper-dependent cell death mechanism that has found application in cancer immunotherapy through induction of mitochondrial stress and activation of the cGAS-STING pathway." (PMID 41007722, 2025). "Innate immune sensors, such as RIG-I and cGAS have been described as mediators of immune cell-related death of cancer cells and promoters of TBK1 pathways." (PMID 41361170, 2025). "The activation of the cGAS-IFN-I pathway has been actively pursued as a treatment strategy for various types of cancers." (PMID 40282455, 2025). "This review underscores the potential of nanomaterial-based cGAS-STING therapeutics for cancer treatment and identifies key research priorities to address existing limitations and propel the field forward." (PMID 40831989, 2025). "DNA damage has been reported to also promote chemokine expression in many cancer types; in many cases, this is reported to be through the cGAS-STING pathway." (PMID 40507298, 2025). "We refer readers to a recent excellent review for detailed discussion of the detrimental outcomes of cGAS-STING in cancer." (PMID 40552295, 2025). "According to recent studies, SMARCAL1 limits endogenous DNA damage and prevents signaling that is dependent on cGAS-STING during the growth of cancer cells." (PMID 39994264, 2025). "This review highlights a novel groundbreaking therapeutic possibilities through activating cGAS-STING in cancers." (PMID 40552295, 2025). "With the promising results of early agonists, the cGAS-STING pathway has become a major focus in cancer immunotherapy." (PMID 41009575, 2025). "This review examines the contrasting roles of the cGAS-STING signaling pathway in intestinal inflammation and colitis-associated cancer (CAC), emphasizing its promise as a target for cancer prevention strategies." (PMID 40507791, 2025). "In order to expand the application of cGAS-STING-related drugs in cancer treatment, researchers have combined STING agonists with other therapies to create more diverse and effective treatment options." (PMID 40052963, 2025). "This review summarizes recent advances in cGAS‐STING agonist‐based nanotherapeutics for cancer combination therapy." (PMID 40842018, 2025). "While the article outlines these functions in cancer, it provides limited detail, suggesting that a deeper review is needed to fully understand cGAS-STING’s roles and therapeutic potential in reproductive cancers." (PMID 39949780, 2025). "The epigenetic silencing of cGAS-STING represents a pervasive mechanism of immune evasion in cancer." (PMID 40846966, 2025). "Here, we provide the first evidence to our knowledge that CDK12 inactivation activates the cGAS/STING pathway, which in turn drives T cell recruitment in CDK12-deficient cancers." (PMID 40955658, 2025). "Our objective is to establish a mechanistic and translational framework for integrating cGAS–STING activation into cancer immunotherapy strategies to overcome resistance to ICIs." (PMID 41204180, 2025). "SN38-PROTAC treatment induced DAMP secretion from cancer cells, which activated cGAS-STING signaling in bone marrow-derived dendritic cells (BMDCs)." (PMID 41276688, 2025). "The TPP-Ce6 complex provides targeting to the mitochondria of cancer cells, where ROS are generated upon irradiation, leading to mitochondrial damage, activation of the cGAS-STING pathway, and activation of ICD." (PMID 41007722, 2025). "Previous studies have shown that the DNA damage response activates innate immunity through the cGAS–STING pathway in cancers." (PMID 41024256, 2025). "This study reports that mechanical force‐induced nuclear deformation in capillaries leads to cGAS activation in carcinoma cells which exacerbates liver metastasis via facilitating splenocyte migration into liver." (PMID 39737867, 2025). "To further validate mechanical force‐induced activation of the cGAS pathway, we detected components of cGAS pathway in carcinoma cells under high compression." (PMID 39737867, 2025).